IGF1 (insulin like growth factor 1)
Diseases named in the same sentence as IGF1 in open-access papers (continued):
Sharing a sentence is not in itself a finding about the gene and the disease.
acromegaly (continued). "Growth hormone (GH) is nonphysiologically increased in acromegaly, stimulating target tissues directly and indirectly via insulin‐like growth factor type 1 (IGF‐1)." (PMID 37808394, 2023). "In general, biochemical diagnosis of acromegaly is based on the elevation of IGF-1 concentrations and the absence of GH suppression after OGTT." (PMID 37543629, 2023). "In the last visit, for overall patients with cancers, GH (median: 1.50 vs. 0.90 ng/ml, p = 0.017) and IGF-1 (IGF-1, median: 252 vs. 214 ng/ml, p = 0.050; ULN, 1.01 vs. 0.91, p = 0.070) tended to elevate, but the acromegaly-controlled rate was similar (46.4% vs. 52.8%)." (PMID 37442901, 2023). "The median ANGPTL-8, GH, and IGF-1 levels of the patients with NAFLD were lower than those without NAFLD in the whole acromegaly group." (PMID 37590020, 2023). "It is notable that the results of IGF-1 in patients with pharmacological acromegaly treatment were not significantly different than in ones with newly diagnosed acromegaly." (PMID 37373574, 2023). "These guidelines focus the determination of serum IGF-1 to rule out acromegaly in patients with suspicious clinical features, coexistence of several associated conditions/complications of acromegaly and/or in the diagnosis of a pituitary mass." (PMID 36973824, 2023). "Other medical therapies such as pegvisomant (GH receptor antagonist) and cabergoline (dopamine agonist) improve IGF-1 in a subset of patients with medication resistant acromegaly, but rates of biochemical non-remission range from 25–40% in this cohort." (PMID 37104368, 2023). "However, in acromegaly, in which treatment with a long-acting somatostatin analog (octreotide) is used, a reduction in OST via lowered IGF-1 levels was observed." (PMID 37510722, 2023). "In acromegaly, chronic overproduction of GH/IGF-1 leads to increased bone turnover and negative calcium balance." (PMID 37670889, 2023). "We had several differential diagnoses for his clubbing and fascial features, including acromegaly (which is characterized by larger bones of the face, skull, and limbs with jaw prognathism and high IGF‐1 with hormonal disruption), which was ruled out." (PMID 37220512, 2023). "Of the 60 patients who did not receive any medical treatment for acromegaly at five-year, the median IGF-1/ULN was 0.8 (0.6–0.9, range: 0.2–1.3) and median GH was 0.5 (0.2–1.3) μg/L." (PMID 37665404, 2023). "At the diagnosis of acromegaly, random GH, nadir GH, and IGF-1 levels were similar in patients with or without cancers." (PMID 37442901, 2023). "Patients with acromegaly with proliferative retinopathy had higher GH, IGF-1, and HbA1c levels than those without proliferative retinopathy." (PMID 35248150, 2022). "An oral glucose tolerance test (OGTT) can be used in cases of equivocal IGF-1 values, and the absence of GH suppression to <1 μg/L is indicative of acromegaly." (PMID 38983521, 2022). "A diagnosis of acromegaly is confirmed biochemically by detection of increased serum IGF-1 concentrations and high serum levels of GH that are not suppressed in an OGTT." (PMID 35370935, 2022). "We performed sensitivity analysis by excluding patients with acromegaly, and the results showed that the relationship between IGF-1 levels and IVS thickening is independent of acromegaly." (PMID 36568107, 2022). "According to the results of our study, the addition of cabergoline to SSA normalized IGF-1 levels in a considerable amount of acromegaly patients with a moderately elevated IGF-1 level, regardless of serum PRL levels." (PMID 35612842, 2022). "In conclusion, medical treatment is generally required when surgery fails to normalize GH/IGF-1 levels in patients with acromegaly." (PMID 35612842, 2022). "In healthy patients who do not have acromegaly, administering exogenous growth hormone stimulates a rise in IGF-1, and patients can subsequently develop carpal tunnel syndrome." (PMID 36043126, 2022).
acromegaly (continued). "In our work, neither the age (using an arbitrary cutoff of 75 years old) changed acromegaly clinical presentation in terms of tumor size or GH/IGF-1 circulating concentrations, nor was the overall response to treatment different at very advanced ages." (PMID 36187107, 2022). "When the normal GH/IGF-1 levels are not achieved in acromegaly patients after surgery, either SSA or pegvisomant is recommended as an adjuvant treatment/therapy." (PMID 35612842, 2022). "Younger age at diagnosis, male sex, lower GH, IGF-1 and PRL concentrations, smaller tumor size at diagnosis as well as positive α-SU staining, lower Ki-67 index and DG tumors predicted better treatment outcome in acromegaly patients." (PMID 36187106, 2022). "Logistic regression analysis also suggested that the FABP-4 level is an independent predictor of DM in acromegaly but not age, sex, IGF-1, and GH." (PMID 34217172, 2021). "In this study we analyze a series of 94 patients with acromegaly who underwent surgical resection of pituitary adenomas between June 1999 and December 2019 in order to better understand the predictive value of POD1 GH and IGF-1 levels." (PMID 34867787, 2021). "With the emergence of the ultrasensitive assays, the present GH and IGF-1 assays in combination with the new GH and IGF-1 standards are much more precise and provide more accurate tools to diagnose and monitor patients with acromegaly." (PMID 33803429, 2021). "Restricting analyses to 377 602 individuals whose IGF-1 was measured from their first aliquot did not alter conclusions drawn, nor did removing those with acromegaly, endocrine-related arthropathies or restricting to the MR population." (PMID 33027520, 2021). "A study evaluating the French acromegaly population has suggested that age, BMI, and hypertension were predictors of DM presence, but not IGF-1 and GH." (PMID 34217172, 2021). "When SSAs fail to control acromegaly, PEG normalized serum IGF1 levels in 70–97% of cases." (PMID 33869029, 2021). "Dichotomized age, IGF-1 levels at diagnosis, and tumor T2-weighted signal are reliable predictors of both >50% IGF-1 reduction and linear % IGF-1 reduction after 6 month fg-SRL treatment in naïve acromegaly patients." (PMID 34025586, 2021). "In a study of 16 male patients with refractory acromegaly, despite conventional therapy, the addition of clomiphene citrate, a SERM, reduced IGF-1 levels by 41% but caused a nonsignificant increase in GH levels." (PMID 33910628, 2021). "In our series, we described numerous patients with high IGF-1 levels despite no clear clinical suspicion of acromegaly (GR2)." (PMID 34081617, 2021). "Although the relationship between acromegaly and depression has been ascribed to the effects of chronic disease, the role of growth hormone (GH), and insulin like growth factor-1 (IGF-1) is not clear." (PMID 34248479, 2021). "A recent study showed that the incidence of central hypothyroidism was 8.7% among acromegaly patients, far lower than that in NFPA patients, which might result from the stimulation effect of GH/IGF-1 on thyroid function." (PMID 35154007, 2021). "As the deterioration in bone microstructure due to prolonged GH/IGF-1 exposure was not fully reversible, clinicians should be aware of the bone fragility of acromegaly patients even after they had achieved biochemical remission." (PMID 34603213, 2021). "Unfortunately, comparable statistics of IGF-1 for acromegaly have not been found, but our results suggest an excellent diagnostic performance using the three ECS-complex proteins SOCS2, cullin-5 and Rbx-2 in conjunction." (PMID 33671326, 2021). "In 1 patient (1%) pathology was not available, but elevated preoperative IGF-1 levels consistent with acromegaly decreased postoperatively to within normal limits." (PMID 34867787, 2021). "Severe obesity, malnutrition, and prolonged fasting can reduce IGF-1 levels in patients with and without acromegaly." (PMID 33803429, 2021).
acromegaly (continued). "There is no family history of gigantism or acromegaly, and all affected patients had an IGF-1 within the age-adjusted reference range." (PMID 33010004, 2021). "The prevalence of normal IGF-1 levels at last follow-up was not different between Acropara and isolated acromegaly." (PMID 32311048, 2020). "In conclusion, GH/IGF1 excess did not exert a protective effect on periodontal status in patients with active acromegaly, possibly due to concurrent hypogonadism and opposing effects of proinflammatory and antiinflammatory cytokines." (PMID 33154456, 2020). "The net effect of acromegaly on inflammation and CVD seems to be influenced by disease control (GH/IGF-1 levels), concomitant metabolic disturbances, hormonal deficiencies, age and gender, which illustrates the complex mechanisms and interactions with GH/IGF-1 and other factors." (PMID 32458292, 2020). "In this study, we found that, in the included acromegaly patients, the levels of GH and IGF-1 were not correlated with the occurrence of cardiac abnormalities or quantitative cardiac parameters." (PMID 32148485, 2020). "Our study demonstrated that GH/IGF1 excess in patients with acromegaly did not exhibit a protective effect on periodontal health." (PMID 33154456, 2020). "The third patient was a 64-year-old-Asian woman who presented with serum growth hormone 6.0 ng/ml and insulin-like growth factor 1 of 341 ng/ml, but no characteristic features of acromegaly." (PMID 30862315, 2019). "At the last follow-up, patients were divided into 3 groups based on their acromegaly remission statuses after surgery: the remission group (26/64, 40.6%), the GH/IGF-1 discordant group (8/64, 12.5%), and the non-remission group (30/64, 46.9%)." (PMID 31736874, 2019). "Therefore, we aimed to examine the correlation between IGF-1 levels and BMD in humans and to explore other factors that affect BMD in patients with acromegaly." (PMID 31781204, 2019). "Some other studies have shown that lumbar-spine BMD is negatively correlated with the duration of hypogonadism, positively correlated with the duration of acromegaly, but not correlated with the IGF-1 level." (PMID 31781204, 2019). "The second patient was a 40-year-old-Asian woman who presented with serum growth hormone 31.14 ng/ml and insulin-like growth factor 1 of 709.6 ng/ml, but no characteristic features of acromegaly." (PMID 30862315, 2019). "Surprisingly, the enlarged hip dimensions (FW and HAL) in active acromegaly were not correlated with GH or IGF‐1 levels." (PMID 31844828, 2019). "There are multiple treatment modalities for acromegaly and the current consensus on the treatment goals include normalization of IGF-1 levels, reduction of GH levels below 1.0 ug/L, decrease of tumour volume, and improvement of clinical signs and symptoms." (PMID 31939490, 2019). "The first patient was a 48-year-old-Asian woman who presented with serum growth hormone 6.99 ng/ml and insulin-like growth factor 1 of 476 ng/ml, but no characteristic features of acromegaly." (PMID 30862315, 2019). "We have expanded the national registry of patients with acromegaly treated with PEGV, from our first experience in 2010 when we analyzed the outcome of 28 patients with acromegaly treated with PEGV for a mean treatment duration of 12 months, achieving IGF-1 normalization in 58.8 % of them." (PMID 31460622, 2019). "A prospective, randomized, double-blind study compared OCT and PAS activity in 358 patients from 27 different countries, by enrolling medically naive acromegaly patients with GH >5 μg/L or GH nadir ≥1 μg/L after an oral glucose tolerance test (OGTT), and IGF-1 above the upper normal limit." (PMID 31412614, 2019). "Femoral neck BMD is positively correlated with the IGF-1 level and not correlated with the duration of hypogonadism and the duration of acromegaly." (PMID 31781204, 2019).
acromegaly (continued). "In contrast, a decline in cortical thickness in the neck was observed in acromegaly following GH‐lowering treatment, and CBTneck and CBTcalcar were no longer correlated with GH and IGF‐1 1‐year PO." (PMID 31844828, 2019). "Regarding the nonautonomous thyroid changes in acromegaly, we are the first to show that IGF-1 has a significant influence on thyroid endocrine function, especially on serum T3." (PMID 29593792, 2018). "Although the two earlier discovered analogs, octreotide and lanreotide, are the most widely used medical therapy for acromegaly, they do not normalize GH and IGF-1 levels in a significant percentage of patients with acromegaly." (PMID 30232095, 2018). "In conclusion, in acromegaly HSI is mainly related with IR and the reduction of GH and IGF-1 levels, and above all the improvement in insulin sensitivity leads to an improvement of this surrogate index of hepatic steatosis, which should always be evaluated in the follow-up of acromegalic patients." (PMID 30662461, 2018). "Treatment with GH, on the other hand, aims to normalize IGF-1 levels as much as possible and is not expected to induce a sustained excess of IGF-1, as in acromegaly or in patients with diabetic retinopathy." (PMID 29082892, 2018). "Acromegaly with or without gigantism is a disorder characterized by elevated levels of GH and IGF-1." (PMID 28933734, 2017). "None of the 10 patients with persistently elevated IGF-1 and nadir GH > 0.4 μg/L after 5 years developed a phenotype of acromegaly, changes in physiognomy or increase in IGF-1 and no tumor was detected by the imaging methods." (PMID 28977166, 2017). "Current guidelines suggest screening if several acromegaly symptoms are present; therefore, a high number of patients who consult to rule out sleep apnea syndrome would need an IGF-1 test to rule out GH excess." (PMID 28898247, 2017). "In a large, randomized, 12-month, Phase 3 trial (C2305 study) in medically naive patients with acromegaly, pasireotide LAR demonstrated superior biochemical control (composite end point of age-normalized IGF-1 and GH <2.5 ng/mL) in comparison with octreotide LAR (31.3 vs. 19.2 %; P = 0.007)." (PMID 27896545, 2017). "Although most of the pituitary-related hormones were not different, the fasting IGF-1 levels in patients with acromegaly and DI were significantly higher than those in patients without DI (1115.40 ± 253.73 vs. 791.67 ± 206.62, p = 0.020)." (PMID 28620866, 2017). "Although we cannot completely rule out acromegaly in those 5 cases, all IGF-1 elevations were mild and there was no tumor in 4 of the patients and the physicians who cared for those patients decided to follow-up on them with no specific treatment." (PMID 28898247, 2017). "Red blood cell count and hemoglobin concentrations were also raised in acromegaly, and we confirmed that these increased with IGF-1 levels but not GH." (PMID 28733467, 2017). "The biochemical basis of cardiac remodeling and subsequent LVH in acromegaly is not fully established but appears to result, at least in part, as a direct effect of elevated levels of GH and IGF-1 on cardiac cells." (PMID 28279153, 2017). "We analyzed the clinical characteristics of the 7 patients with persistently elevated IGF-1 (5 without a confirmed diagnosis of acromegaly and 2 with confirmed diagnosis) and compared them with the rest of the patients (n = 1470)." (PMID 28898247, 2017). "A second patient with persistently high IGF-1 (2.8 times the upper limit of normal [ULN] of the gender and age range) had GH suppression on the OGTT (0.31 ng/mL) but presented a florid symptomatic acromegaly." (PMID 28898247, 2017). "In 2000, the Acromegaly Treatment Workshop proposed a precise international criterion, suggesting a complete hormonal remission rate when OGTT suppressed the GH serum levels lower than 1 μg/ L and a normalization of serum IGF-1 levels occurred." (PMID 27453753, 2016).
acromegaly (continued). "PubMed was searched for English-language studies of a minimum duration of 24 weeks that evaluated ≥10 patients with acromegaly treated with octreotide LAR or lanreotide Autogel from 1990 to March 2015 and reported GH and/or IGF-1 data as the primary objective of the study." (PMID 26519143, 2016). "Pasireotide LAR is significantly (P = 0.007) superior to octreotide LAR at providing GH <2.5 μg/L and normal IGF-1 in patients who have not previously received medical treatment for acromegaly, as shown in the core study." (PMID 27039081, 2016). "In our interpretation of the results, acromegaly was ruled out in 40/42 patients and considered “possible” in only 2/42 (with persistently elevated IGF-1 and microadenoma detected by MRI, but with GH suppression and without clinical or laboratory progression)." (PMID 27982199, 2016). "Elevated IGF-1 does not always indicate acromegaly, but its specificity increases when measured outside puberty and pregnancy (situations characterized by physiological elevation of this hormone)." (PMID 27982199, 2016). "In summary, the case presented here is an extremely rare example of a sporadic pulmonary NET associated with GH and IGF-1 but not GHRH secretion, thereby inducing a clinically florid acromegaly." (PMID 27349224, 2016). "For pasireotid (acromegaly) the PEP was biochemical control (defined as a combination of reduction of the mean growth hormone [GH] level below 2.5 μg/l and normalisation of the age- and sex-adjusted insulin-like growth factor 1 [IGF-1] level after 24 weeks)." (PMID 27842592, 2016). "Excess IGF-1 can result in acromegaly, a condition characterized by excessive growth, while lack of IGF-1 can result in dwarfism." (PMID 27227831, 2016). "Laboratory tests revealed markedly increased growth hormone (GH) and insulin-like growth factor 1 (IGF-1) without GHRH elevation in the absence of pituitary pathologies confirming the paraneoplastic origin of clinical presentation with acromegaly." (PMID 27349224, 2016). "The very slight elevation in IGF-1, in the absence of any clinical features of acromegaly, was felt most likely to be a nonsignificant result." (PMID 26770843, 2015). "No matter how the control of acromegaly is achieved, suppression of IGF-1 should be mandatory in acromegalic patients with cancer." (PMID 25962899, 2015). "In addition to effects on GH and IGF-1, both pasireotide LAR and octreotide LAR provided overall clinical benefit by effectively improving the signs and symptoms of acromegaly and reducing tumor volume." (PMID 25103549, 2015). "In this cross-sectional study of newly diagnosed patients with active acromegaly based on clinical presentation, unsuppressed GH levels during an OGTT, and elevated age-matched immunoreactive total IGF1 levels, IGF1 bioactivity was within the reference range in a considerable number of patients." (PMID 24692508, 2014). "Increased serum IGF-1 levels in patients with acromegaly may downregulate IGF-1Rβ; however, the autocrine and paracrine effects of IGF-1 can be induced by local expression of IGF-1Rβ in tumor tissue." (PMID 25329702, 2014). "However, despite this valuable information, these studies demonstrate conditions in which the changes in GH and IGF-1 paralleled, namely both decreased as seen in states of GHD, or increased as seen in acromegaly." (PMID 24341939, 2014). "The acromegaly-related genetic background alone (notably a systemic or local GH/IGF-1 overproduction) is probably not enough to trigger the onset of follicular epithelial cell-derived cancer." (PMID 25019383, 2014). "This 49-year-old man with acromegaly diagnosed at age 34, never achieved normal levels of IGF-1 and GH despite two surgeries and radiotherapy after initially receiving suboptimal pharmacological therapy." (PMID 24052243, 2014).